SLU7 (spliceosome associated SLU7)
Description:
Required for pre-mRNA splicing as component of the spliceosome. Participates in the second catalytic step of pre-mRNA splicing, when the free hydroxyl group of exon I attacks the 3'-splice site to generate spliced mRNA and the excised lariat intron. Required for holding exon 1 properly in the spliceosome and for correct AG identification when more than one possible AG exists in 3'-splicing site region. May be involved in the activation of proximal AG. Probably also involved in alternative splicing regulation.
Synonyms: hSlu7; 9G8
Tractability: Small molecule: a structure with a bound ligand is known. PROTAC: UniProt records ubiquitination sites on it; ubiquitination databases record sites on it; its protein half-life has been measured.
Gene: Protein-coding gene on chromosome 5 (160,401,641 to 160,421,711, reverse strand). Ensembl gene ENSG00000164609.
Subcellular location: Nucleus; Nucleus speckle; Cytoplasm
Subcellular location (Human Protein Atlas): Nucleoplasm; Nuclear speckles
Pathways (Reactome):
Metabolism of RNA: Transport of Mature mRNA derived from an Intron-Containing Transcript; mRNA 3'-end processing; mRNA Splicing - Major Pathway
Gene Ontology:
Molecular function: pre-mRNA 3'-splice site binding; protein binding; second spliceosomal transesterification activity; zinc ion binding
Biological process: alternative mRNA splicing, via spliceosome; cellular response to heat; intracellular protein transport; mRNA 3'-splice site recognition; RNA splicing, via transesterification reactions; mRNA cis splicing, via spliceosome; mRNA splicing, via spliceosome; RNA splicing
Cellular component: catalytic step 2 spliceosome; cytoplasm; membrane; nuclear speck; nucleoplasm; nucleus; post-spliceosomal complex; small nuclear ribonucleoprotein complex; spliceosomal complex; U2-type catalytic step 1 spliceosome; U2-type catalytic step 2 spliceosome
Genetic constraint (gnomAD): Loss-of-function variants: 33 observed, 56.56 expected, observed/expected ratio (o/e) 0.58, 90% interval 0.44 to 0.78. The upper end of that interval is the gene's LOEUF score, 0.78, which puts it in group 3 of 6, group 1 being the genes least tolerant of losing a copy. Missense variants: 348 observed, 528.46 expected, observed/expected ratio (o/e) 0.66, 90% interval 0.6 to 0.72. Synonymous variants: 144 observed, 174.66 expected, observed/expected ratio (o/e) 0.82, 90% interval 0.72 to 0.95.
Homologues: Orthologues: chimpanzee SLU7 (99% identical), macaque SLU7 (99% identical), dog SLU7 (98% identical), rabbit SLU7 (97% identical), pig SLU7 (97% identical), mouse Slu7 (96% identical), rat Slu7 (96% identical), guinea pig SLU7 (95% identical), tropical clawed frog slu7 (81% identical), zebrafish slu7 (77% identical), Drosophila melanogaster Slu7 (52% identical), Caenorhabditis elegans sluh-7 (44% identical).
Diseases named in the same sentence as SLU7 in open-access papers:
SLU7 is named in the same sentence as 119 diseases in open-access papers, as found by Europe PMC text mining. Sharing a sentence is not in itself a finding about the gene and the disease. The quoted sentences say what the papers report.
hepatocellular carcinoma (13 papers, 2018 to 2025). A malignant tumor that arises from hepatocytes. "Thus, the downregulation of SLU7 levels described during chronic liver disease and hepatocellular carcinoma (HCC) explains, in part, the accumulation of DeltaTAp73 transcripts in these pathologic conditions, which could contribute to carcinogenesis as demonstrated in mice." (PMID 36362191, 2022).
bladder cancer (3 papers, 2021 to 2025). "In bladder cancer, G3BP1 collaborates with SLU7 to activate the PI3K/AKT pathway, leading to reduced MHC-I expression and facilitating immune escape." (PMID 40346580, 2025).
liver disease (2 papers, 2022 to 2024). "Finally, we discuss the implications of SLU7 in pathophysiology, with particular emphasis on the progression of liver disease and its possible role as a therapeutic target in human cancer." (PMID 36362191, 2022).
alcoholic steatohepatitis (1 paper, 2021). "In contrast to cirrhosis, SLU7 was shown to be elevated in alcoholic steatohepatitis in humans, and SLU7 knockdown prevented oxidative stress and liver damage in alcohol-treated mice." (PMID 33716968, 2021).
Cirrhosis (1 paper, 2021). A chronic disorder of the liver in which liver tissue becomes scarred and is partially replaced by regenerative nodules and fibrotic tissue resulting in loss of liver function. "SLU7 is a splicing factor that ensures the correct selection of the 3′ splice site, and its expression was downregulated in patients with cirrhosis." (PMID 33716968, 2021).
Crohn disease (1 paper, 2022). A gastrointestinal disorder characterized by chronic inflammation involving all layers of the intestinal wall, noncaseating granulomas affecting the intestinal wall and regional lymph nodes, and transmural fibrosis. "Therefore, the different expression patterns of SLU7 in these two inflammatory bowel diseases pointed to SLU7 as a potential discriminator between ulcerative colitis and Crohn’s disease." (PMID 36362191, 2022). "Remarkably, in the mucosa of patients with Crohn’s disease, SLU7 was downregulated in inflamed tissues but not in non-inflamed tissues." (PMID 36362191, 2022).
ulcerative colitis (1 paper, 2022). An inflammatory bowel disease involving the mucosal surface of the large intestine and rectum. "SLU7 was found downregulated in the colonic mucosa of patients with ulcerative colitis independent of the inflammation status of the tissue." (PMID 36362191, 2022).
cancer (128 papers, 2009 to 2026). A tumor composed of atypical neoplastic, often pleomorphic cells that invade other tissues. "Accordingly, the aberrant expression of SLU7 could be associated with human diseases including cancer, although strikingly, it is an essential survival factor for cancer cells." (PMID 36362191, 2022). "Moreover, the downregulation of SLU7 can damage liver glucometabolic and lipid metabolism disorders, and increase the risk of cancer." (PMID 32284746, 2020). "Our RNA-crosslinking immunoprecipitation (RNA-CLIP) study in cancer cells revealed that SLU7 directly binds C13orf25 mRNA to ensure the expression of transcript B and the generation of the miRNAs implicated in cancer cell survival." (PMID 36362191, 2022). "Surprisingly, we found that SLU7 regulates DNA methylation and, therefore, SLU7 silencing in a wide variety of cancer cells, resulting in a general DNA hypomethylation." (PMID 36362191, 2022). "Again, experiments performed with normal mouse liver cells as well as in a wide variety of cancer cells of different origins demonstrate that SLU7 is a core factor in the preservation of genome integrity acting at different levels." (PMID 36362191, 2022). "Moreover, we revise the implications of SLU7 in liver pathophysiology and its possible role as a therapeutic target in human cancer." (PMID 36362191, 2022). "In fact, SLU7 knockdown could recapitulate many events that have been proposed separately as anti-cancer strategies, including global DNA demethylation, induction of R-loop formation, DNA damage, cell cycle arrest, mitotic stress, autophagy and apoptosis." (PMID 36362191, 2022). "Future studies should help to elucidate whether, as suggested, SLU7 represents a pan-cancer therapeutic target." (PMID 36362191, 2022). "Importantly, SLU7 is also essential to ensure cell cycle progression of cancer cells of different origins." (PMID 36362191, 2022). "Therefore, SLU7 could represent a cancer cell’s vulnerability, and the silencing of SLU7 could represent a new therapeutic strategy." (PMID 36362191, 2022). "Moreover, SLU7 could represent a cancer cell’s vulnerability to be therapeutically explored." (PMID 36362191, 2022). "However, it is important to highlight that, perhaps due to these central and pleiotropic roles linked to cell proliferation, SLU7 is a non-redundant survival factor for human cancer cells of very different origins and does not affect the viability of normal cells." (PMID 36362191, 2022).
SLU7 also shares sentences with these, for which no sentence is quoted: tumor (49 papers); myelodysplastic syndrome (26); breast carcinoma (19); acute myeloid leukemia (13); myeloid malignancies (11); lung carcinoma (9); colon cancer (8); leukemia (8); ovarian carcinoma (8); glioblastoma (7); glioma (7); hematological malignancies (7); chronic lymphocytic leukemia (6); infection (6); melanoma (6); pancreatic cancer (6); prostate carcinoma (6); colorectal cancer (4); gastric cancer (4); lung adenocarcinoma (4); neuroblastoma (4); retinitis pigmentosa (4); autism spectrum disorder (3); cardiomyopathies (3); developmental delay (3); Parkinson disease (3); renal carcinoma (3); retinal degeneration (3); anaemia (2); autism (2).
A further 81 diseases each share a sentence with SLU7 in 2 papers or fewer.